POMT1 (protein O-mannosyltransferase 1)
Diseases named in the same sentence as POMT1 in open-access papers:
POMT1 is named in the same sentence as 60 diseases in open-access papers, as found by Europe PMC text mining. Sharing a sentence is not in itself a finding about the gene and the disease. The quoted sentences say what the papers report.
dystroglycanopathies (19 papers, 2013 to 2026). "Finally, the question remains whether our data could provide structural and functional explanations for mutations in the human POMT1/2 homologs that cause α-dystroglycanopathies." (PMID 33357379, 2020). "Our results from a preclinical mouse model of dystroglycanopathy, describe a progressive cardiac disease in sedentary Pomt1 cKO mice, however prior to overt disease development, contractile stress can instigate cardiomyofiber injury and dysfunction." (PMID 38771868, 2024). "Due to the progressive nature of cardiac disease often observed in patients with dystroglycanopathies and our Pomt1 cKO mice, we set out to examine the importance of O-mannosylated DG in preventing myofiber injury and aberrant remodeling." (PMID 38771868, 2024). "Other genes contributing to dystroglycanopathies through glycosylation errors include POMT1, POMT2, POMGNT1, FKRP, ISPD and LARGE1." (PMID 38439105, 2024). "LGMD R7 telethonin-related was found in 14.6% (6/41) of index patients, and dystroglycanopathies (including mutations in FKRP, POMT1, POMT2 and ISPD) were found in 12.2% (5/41) of index patients." (PMID 37974208, 2023). "Due to the enrichment of regulatory variants in FKTN and DTNA, we expanded our search to additional dystroglycanopathy genes (LARGE1, POMT1, POMT2) and identified two regulatory variants of interest in LARGE1 in gene-elusive cases." (PMID 35288587, 2022). "Another candidate experimental therapy – overexpression of the LARGE enzyme – has been shown to restore αDG function in a variety of α-dystroglycanopathies caused by mutations in FKRP, FKTN, POMGNT1 and POMT1." (PMID 32423971, 2020). "In 2002, mutations of the POMT1 were found to be associated with Walker-Warburg syndrome (WWS), considered the most severe subgroup of dystroglycanopathies." (PMID 31311558, 2019). "Our large cohort confirms the importance of type and location of each POMT1 mutation for the individual clinical manifestation and thereby expands the knowledge on the genotype-phenotype correlation in POMT1-related dystroglycanopathies." (PMID 31311558, 2019). "POMT1–related disorders belong to the group of dystroglycanopathies characterized by a proximally pronounced muscular dystrophy with structural or functional involvement of the brain and/or the eyes." (PMID 31311558, 2019). "The phenotypic severity of POMT1-related dystroglycanopathies depends on the residual enzyme activity." (PMID 31311558, 2019). "Similar results have previously been reported in dystroglycanopathy patients with Protein-O-mannosyl transferase 1 (POMT1), Protein-O-mannosyl transferase 2 (POMT2), POMGnT1, FKTN and FKRP mutations." (PMID 30553274, 2018). "Loss of function (LOF) variants in either POMT1–2 or POMGNT2 cause Walker Warburg Syndrome (WWS), the most severe dystroglycanopathy that is associated with profound brain and eye malformations including cobblestone lissencephaly, hydrocephalus, cerebellar hypoplasia, and retinal defects." (PMID 41533692, 2026). "(d) Several subtypes of LGMDs are dystroglycanopathies, primarily caused by mutations in eight genes, including FKRP (R9), POMT1 (R11), FKTN (R13), POMT2 (R14), POMGnT1 (R15), GMPPB (R19), ISPD (R20), and POMGNT2 (R24), involved in the glycosylation of the alpha-dystroglycan pathway." (PMID 37974208, 2023). "Hypoglycosylation of α-dystroglycan (α-DG) resulting from deficiency of protein O-mannosyltransferase 1 (POMT1) may cause severe neuromuscular dystrophies with brain and eye anomalies, named dystroglycanopathies." (PMID 29867208, 2018). "Among dystroglycanopathies, good correlation between α-DG staining and disease course was demonstrated in only a few forms (POMT1, POMT2, and POMGnT1-mutated cases), and is absent in patients with mutations in FKRP and FKTN." (PMID 26404900, 2015).
Walker–Warburg syndrome (16 papers, 2007 to 2026). "Mutations in human POMT1, a homologue of the yeast Pmt4, cause Walker-Warburg Syndrome (WWS), which is characterized by severe congenital muscular dystrophy, neuronal migration defects, and structural abnormalities of the eye." (PMID 21977037, 2012). "POMT1 encodes a glycosyltransferase, adding O-mannosyl glycans to dystroglycan (DG), whose deficiency causes muscular dystrophy and neural migration defects (Walker–Warburg syndrome)." (PMID 39859496, 2025). "P14 had a homozygous RAG1 pathogenic variant as well as POMT1-associated muscle-eye-brain disease." (PMID 34539671, 2021). "For instance, in D. melanogaster, POMT1 and POMT2 are required for maintaining the integrity of larval muscles and normal axonal connections of sensory neurons, while in humans, mutations in POMT1 and POMT2 lead to Walker–Warburg syndrome." (PMID 33922798, 2021). "The clinical, neuroradiological, and genetic findings of 35 patients with biallelic POMT1 mutations (15 WWS, 1 MEB (muscle-eye-brain disease), 19 LGMD) from 27 independent families are reported." (PMID 31311558, 2019). "Regarding Walker-Warburg syndrome (WWS), Wairkar and co-workers performed a screen for synaptic abnormalities in Drosophila and identified mutations in POMT1 orthologue, rotated abdomen (rt)." (PMID 25859781, 2015). "For example, sequence analysis of the POMT1 gene identified a copy of a c.2167dupG mutation in exon 20 in a patient with Walker-Warburg syndrome (WWS) (data not shown)." (PMID 24304607, 2013). "Among those are POMT1/POMT2 and POMGNT1, the major disease-causing factors of the Walker–Warburg syndrome (WWS; lacking classic O-mannose glycans), and MEB (no elongation of O-linked mannoses), respectively." (PMID 33610554, 2021).
muscular dystrophy (14 papers, 2015 to 2025). Muscular dystrophy (MD) refers to a group of more than 30 genetic diseases characterized by progressive weakness and degeneration of the skeletal muscles that control movement. "Two fetuses were identified with a pathological genetic result (one with trisomy 18 and one with POMT1-gene-variant in a family with members affected by muscular dystrophy)." (PMID 41107504, 2025). "Patient #46 underwent a congenital muscular dystrophy panel and was found to have a pathogenic variant in POMT1, a gene that has been associated with congenital cataracts." (PMID 36980880, 2023). "It has been shown that the mutation of POMT1 results in muscular dystrophy and associated neural defects in the mammals." (PMID 30891062, 2019). "Genetic defects in either protein O-mannosyltransferase, POMT1 or POMT2, underlie severe muscular dystrophies in humans." (PMID 31959160, 2020). "Furthermore, we mimicked two POMT1 amino acid exchanges (G76R and V428D) that result in severe congenital muscular dystrophies in humans, in yeast Pmt4 (I112R and I435D)." (PMID 27358400, 2016). "Amongst these was a SNP in POMT1 (Protein-O-Mannosyltransferase 1) which produces the POMT enzyme complex, dysregulation of which can contribute to the formation of abnormal basement membranes, which can lead to muscular dystrophy." (PMID 26582102, 2015). "However, some studies demonstrate that FKTN, POMT1, and DAG1 are involved in muscular dystrophy." (PMID 29949603, 2018).
congenital muscular dystrophy (6 papers, 2019 to 2025). A muscular dystrophy that is characterized by diminished muscle tone (hypotonia), progressive muscle weakness and degeneration (atrophy), abnormally fixed joints, spinal rigidity, and delays in reaching motor milestones such as sitting or standing unassisted. "In humans, mutations in POMT1 can cause various congenital muscular dystrophy phenotypes, including brain and eye abnormalities." (PMID 40993721, 2025). "Causative variants were found in nine patients with congenital muscular dystrophy in the ACTA1 gene (in one patient), GFPT1 (in one patient), PIGY (in two patients), POMT1 (in one patient), MCU1 (one patient), RYR1 (one patient), and TTN (one patient)." (PMID 37989827, 2024). "From 2005 on, the phenotypic spectrum of POMT1-dependent diseases was expanded as milder forms of limb girdle muscular dystrophy (LGMD2K, 1; MDDGC1; OMIM 609308) and congenital muscular dystrophy (CMD type B1; MDDGB1; OMIM 613155) were described." (PMID 31311558, 2019).
limb-girdle muscular dystrophy (4 papers, 2019 to 2025). Limb-girdle muscular dystrophy (LGMD) is a heterogeneous group of muscular dystrophies characterized by proximal weakness affecting the pelvic and shoulder girdles. "Specifically, mutations in the POMT1 gene result in limb-girdle muscular dystrophy (LGMD R11 POMT-1 related) and Walker Warburg Syndrome (WWS), which presents with brain and eye abnormalities." (PMID 39789642, 2025). "While the CAPN3 variant can explain adductor, posterior thigh weakness, and scapular winging, POMT1 variants are known to be associated with hypertrophic calves in limb-girdle muscular dystrophy (LGMDR11)." (PMID 33250842, 2020). "Although the underlying mechanism remains unclear, POMT1 was reported to associate with the presentation of cardiomyopathy among patients with limb-girdle muscular dystrophy." (PMID 35207686, 2022).
muscle-eye-brain disease (4 papers, 2015 to 2021). "Mutations in the human POMT1 cause not only Walker-Warburg syndrome (WWS) but also muscle-eye-brain disease (MEB)." (PMID 26134523, 2015).
cardiomyopathy (3 papers, 2017 to 2024). A disease of the heart muscle or myocardium proper. "Therefore, to evaluate how the loss of O-mannosylated DG in cardiac muscle affects the development and progression of cardiomyopathy, we generated mice in which the Pomt1 gene was deleted specifically in striated muscle (Pomt1 cKO)." (PMID 38771868, 2024).
muscular dystrophy-dystroglycanopathy (3 papers, 2021 to 2025). "Pathogenic variants in POMT1 are a known cause of Muscular dystrophy-dystroglycanopathy (limb-girdle), type C, 1 (OMIM# 609308), which is consistent with the phenotype of affected individuals in this family." (PMID 40730687, 2025). "POMT1 encodes protein O-mannosyltransferase and is associated with muscular dystrophy-dystroglycanopathy." (PMID 33772059, 2021). "POMT1 was reported to be important in a series of metabolic diseases called muscular dystrophy-dystroglycanopathies (MDDGs), accompanied by variable degrees of intellectual disability, with brain and ocular abnormalities." (PMID 35207686, 2022).
cobblestone lissencephaly (2 papers, 2019 to 2022). "This assumption is supported by a French pathological study of aborted fetuses with cobblestone lissencephaly that found POMT1 being the most frequent causative gene and also described an overlapping phenotype independent of the affected gene." (PMID 31311558, 2019).
Autoimmunity (1 paper, 2021). The occurrence of an immune reaction against the organism's own cells or tissues. "Here the authors show that these children develop T and B cell autoimmunity against protein-O-mannosyltransferase 1 via cross-reactivity." (PMID 33863907, 2021). "Finally, vaccinees have increased antibody levels against human POMT1, suggesting that Pandemrix vaccination triggers POMT1 autoimmunity." (PMID 33863907, 2021). "The results of our study do not exclude a role of autoimmunity to HCRT, but identify with POMT1 another autoantigen in NT1." (PMID 33863907, 2021).
breast carcinoma (1 paper, 2022). "The POMT2 gene (but not POMT1) has been found underexpressed in the breast cancer cell lines MCF7, MDA-MB-231, MDA-MB-253 and T47D, in keeping with observations in samples from patients with breast cancer." (PMID 36494657, 2022).
colon cancer (1 paper, 2022). "The POMT1 mRNA has been reported to be downregulated as a consequence of promoter hypermethylation in the HCT116 cell line of colon cancer, whereas normal colon mucosa cells lacked POMT1 hypermethylation." (PMID 36494657, 2022).
Encephalocele (1 paper, 2020). A neural tube defect characterized by sac-like protrusions of the brain and the membranes that cover it through openings in the skull. "Geis and colleagues discussed the presence of an encephalocele as possibly an indicator of the presence of pathogenic POMT1 mutations in terms of a phenotype-genotype correlation." (PMID 32907597, 2020).
lymphoma (1 paper, 2023). A malignant (clonal) proliferation of B- lymphocytes or T- lymphocytes which involves the lymph nodes, bone marrow and/or extranodal sites. "However, the exact roles and specific functions of FHIP2B, POMT1, TTLL3, CROCC, and CD52 in lymphoma and the molecular mechanisms of their downmodulation upon MyD88L265P expression are not yet fully understood and require further research." (PMID 36982699, 2023).
meningocele (1 paper, 2019). A congenital abnormality in which the meninges protrude through a defect in the spinal column or the cranium. "Remarkably, neural tube defects ranging from meningocele to major occipital meningoencephalocele could be linked to POMT1 in 6/7 cases with an identified mutation." (PMID 31311558, 2019).
meningoencephalocele (1 paper, 2020). A congenital abnormality in which the meninges protrude through a defect in the cranium. "Regarding diseases affecting proper glycosylation of alpha-dystroglycan, the manifestation of a meningoencephalocele has only rarely been associated with defects in known genes such as POMT1 and ISPD." (PMID 32907597, 2020). "The clinical picture of patients with POMT1 variants includes neural tube defects ranging from meningocele to meningoencephalocele." (PMID 32907597, 2020). "Based on our findings as well as previous findings of meningoencephaloceles in patients with POMT1 and ISPD mutations, we recommend an initial laboratory analysis of CK in newborns which present clinically with the combined symptoms of muscular weakness and meningoencephalocele." (PMID 32907597, 2020).
Myocardial fibrosis (1 paper, 2024). "Between 90 to 120 wk of age, Pomt1 cKO displayed myocardial fibrosis along with a nonsignificant increase in heart weight-to-tibial length ratio." (PMID 38771868, 2024).
myopia (1 paper, 2018). "The phenotypic subset associated with myopia (n = 130) was found to represent a set of 119 unique genes since 7 genes (COL2A1, COL11A1, FBN1, LTBP2, POMT1, POMT2, POMGNT1) had two or more associated phenotypes, leading to 11 duplicates." (PMID 29346494, 2018).
occipital encephalocele (1 paper, 2019). "The presence of an occipital encephalocele in a WWS patient might point to POMT1 as causative gene within the different genes associated with WWS." (PMID 31311558, 2019).
tumor (3 papers, 2015 to 2022). "Data mining for 5′-end CpG island methylation of TUSC3, ATRNL1, POMT1 and SAMD4A in cancer cell lines and primary tumors showed that the epigenetic defect was commonly observed among different tumor types in association with the diminished expression of the corresponding transcript." (PMID 30018746, 2018). "We found that a number of the genes associated with αDG glycosylation including POMT1, ISPD, FKTN, B3GNT1, and GYLTL1B, inversely associated with both grade and stage of the tumor (i.e. decreased expression of these genes was associated with greater odds of higher grade and stage)." (PMID 26220087, 2015).
cancer (2 papers, 2018 to 2019). A tumor composed of atypical neoplastic, often pleomorphic cells that invade other tissues. "For example, promoter CpG island hypermethylation-associated silencing of some genes, such as TUSC3 (tumor suppressor candidate 3) and POMT1 (protein O-mannosyltransferase 1), reduce circRNA production in cancer." (PMID 30774645, 2019). "POMT1 was found more frequently methylated in upper aerodigestive tract-derived tumors and esophagus, thyroid and soft tissue-originated cancer cell lines." (PMID 30018746, 2018). "The occurrence of TUSC3, ATRNL1, POMT1 or SAMD4A promoter CpG island hypermethylation was not a restricted in vitro phenomenon of long-cultured cancer cell lines." (PMID 30018746, 2018).
myopathies (2 papers, 2020 to 2025). "Collectively, these observations indicate that the myopathy observed in Pomt1skm mice can be limited or slowed by restoring Pomt1 expression, and that this likely occurs through O-mannosylated DG providing strength to the sarcolemma." (PMID 39789642, 2025).
infection (1 paper, 2021). The state of being infected such as from the introduction of a foreign agent such as serum, vaccine, antigenic substance or organism. "Currently, it remains unknown whether T cell reactivity against POMT1 can be observed in NT1 patients not exposed to influenza A (H1N1) vaccination or infection." (PMID 33863907, 2021).
POMT1 also shares sentences with these, for which no sentence is quoted: Hydrocephalus (2 papers); cardiac disease (1); Cerebellar hypoplasia (1); clear cell carcinoma (1); collagenopathy (1); colon adenocarcinoma (1); colorectal cancer (1); congenital cataracts (1); congenital myopathies (1); Emery-Dreifuss muscular dystrophy (1); Esophageal Carcinoma (1); Filaminopathy (1); genetic diseases (1); glioma (1); Head-Neck Squamous Cell Carcinoma (1); hematological malignancies (1); hyperopia (1); Intellectual disability (1); laminopathy (1); Lissencephaly (1); lysosomal acid lipase deficiency (1); melanoma (1); metabolic disease (1); microtia (1); myotilinopathy (1); narcolepsy type 1 (1); neuronal migration disorder (1); Pallister-Killian syndrome (1); polymicrogyria (1); prostate carcinoma (1).
A further 7 diseases each share a sentence with POMT1 in 1 paper.